HLA-J (major histocompatibility complex, class I, J (pseudogene))
Synonyms: CDA12; HLA-59; formerly HLA-CDA12; D6S203
Gene: Transcribed unprocessed pseudogene on chromosome 6 (30,006,606 to 30,009,539, forward strand). Ensembl gene ENSG00000204622.
Diseases named in the same sentence as HLA-J in open-access papers:
HLA-J is named in the same sentence as 8 diseases in open-access papers, as found by Europe PMC text mining. Sharing a sentence is not in itself a finding about the gene and the disease. The quoted sentences say what the papers report.
breast carcinoma (5 papers, 2020 to 2024). "A few studies have investigated HLA-J and established that its expression is elevated in breast cancer biopsies and that this is associated with the overexpression of estrogen receptor 1 (ESR1), which has immunosuppressive activities." (PMID 34567510, 2021). "In addition, the overexpression of HLA-J after neoadjuvant chemotherapy has been reported to be associated with reduced survival rates in breast cancer, which suggests altered immune evasion caused by HLA-J rs767861647 mutation might be involved in breast cancer progression." (PMID 34567510, 2021).
coronary artery disease (1 paper, 2018). "HLA-J is a pseudogene of HLA-A,59 a gene associated with Graves’ disease, an autoimmune-metabolic disorder of the thyroid gland while RNF39 SNP has recently been associated with non-obstructive coronary artery disease." (PMID 29188820, 2018).
cancer (7 papers, 2017 to 2023). A tumor composed of atypical neoplastic, often pleomorphic cells that invade other tissues. "Notably, HLA-A, HLA-DPA1, HLA-DQB1, HLA-DRA, HLA-DRB1, HLA-DRB5, and HLA-J consistently negatively correlated with the PLK1 expression in the 12 cancer types." (PMID 30631355, 2018). "However, other genes associated with our diagnostic CpGs, such as HLA-J and a non-coding RNA, have not yet been associated with cancer, to our knowledge, and thus, introduce new biological aspects to explore." (PMID 28412973, 2017). "In contrast, HLA-J and ZEB2 dependencies contained substantial dependent cell lines derived from other types of cancer such as pancreas, lung, and liver in addition to a substantial population of skin cells." (PMID 33842927, 2021). "We found that 6 genes (HLA-J, DOA, DOB, DPB1, DQA1, and DQB2) had significantly higher expression levels in the lower-TMB subtype of at least 5 cancer types, while no any HLA gene showed significantly higher expression levels in the higher-TMB subtype of at least 5 cancer types." (PMID 30634925, 2019). "This study demonstrated that miR-19a or miR-19b-1 overexpression in cancer cells led to a general downward trend in the expression profile of MHC Class I molecules (such as HLA-B, HLA-E, HLA-F, HLA-G or HLA-J), which has never been reported in other physiological and pathological processes." (PMID 32308549, 2020).
tumor (2 papers, 2020 to 2023). "In terms of HLA expression, HLA-A, HLA-B, HLA-C, HLA-E, HLA-F, HLA-G, and HLA-J were significantly more highly expressed in C2 than in C1, indicating that tumour subtypes differ in the activation of immune cells." (PMID 37691922, 2023). "Heatmap indicated that NCF1C, HLA-DRB6, HLA-DPB2, HLA-J, HLA-H, HLA-L and RPL13AP20 displayed high expressions in the low-risk group, and thus were categorized as tumor-suppressor pseudogenes in the current study." (PMID 33378744, 2020).
HLA-J also shares sentences with these, for which no sentence is quoted: Graves disease (1 paper); hyperthyroidism (1); Insulin resistance (1); lipoma (1).